GRIN2D (glutamate ionotropic receptor NMDA type subunit 2D)
Description:
Component of N-methyl-D-aspartate (NMDA) receptors (NMDARs) that function as heterotetrameric, ligand-gated cation channels with high calcium permeability and voltage-dependent block by Mg(2+). Participates in synaptic plasticity for learning and memory formation (By similarity). Channel activation requires binding of the neurotransmitter L-glutamate to the GluN2 subunit, glycine or D-serine binding to the GluN1 subunit, plus membrane depolarization to eliminate channel inhibition by Mg(2+). NMDARs mediate simultaneously the potassium efflux and the influx of calcium and sodium (By similarity). Each GluN2 subunit confers differential attributes to channel properties, including activation, deactivation and desensitization kinetics, pH sensitivity, Ca2(+) permeability, and binding to allosteric modulators.
Synonyms: GluN2D; NMDAR2D; NR2D; EB11; DEE46; EIEE46
Tractability: Small molecule: an approved drug acts on it; a structure with a bound ligand is known; a high-quality ligand is known; it belongs to a druggable protein family. Antibody: UniProt places it where antibodies can reach, with high confidence; its Gene Ontology location is reachable by antibodies, with high confidence; UniProt predicts a signal peptide or a membrane-spanning region. PROTAC: ubiquitination databases record sites on it; a small molecule that binds it is known. Other modalities: a drug acting on it is in phase 2 or 3 trials.
Target class: Ion channel; Ionotropic glutamate receptor; Ligand-gated ion channel; NMDA receptor
Safety:
Unwanted effects reported when the protein is acted on. In parentheses: how it was acted on, where the effect was seen, and who reports it.
ataxia (inhibition, acute dosing; central nervous system, cardiovascular; source: Lynch et al. (2017))
convulsions (activation, acute dosing; central nervous system, cardiovascular; source: Lynch et al. (2017))
decreased convulsions (inhibition, acute dosing; central nervous system, cardiovascular; source: Lynch et al. (2017))
decreased memory (inhibition, acute dosing; central nervous system, cardiovascular; source: Lynch et al. (2017))
decreased pain (inhibition, acute dosing; central nervous system, cardiovascular; source: Lynch et al. (2017))
dizziness (inhibition, acute dosing; central nervous system, cardiovascular; source: Lynch et al. (2017))
drug abuse/dependence (inhibition, acute dosing; central nervous system, cardiovascular; source: Lynch et al. (2017))
impaired social interactions (inhibition, chronic dosing; central nervous system, cardiovascular; source: Lynch et al. (2017))
increased blood pressure (inhibition, acute dosing and activation, acute dosing; central nervous system, cardiovascular; source: Lynch et al. (2017))
increased heart rate (inhibition, acute dosing; central nervous system, cardiovascular; source: Lynch et al. (2017))
increased locomotor activity (inhibition, acute dosing; central nervous system, cardiovascular; source: Lynch et al. (2017))
increased then decreased heart rate (activation, acute dosing; central nervous system, cardiovascular; source: Lynch et al. (2017))
neurodegeneration (inhibition, chronic dosing; central nervous system, cardiovascular; source: Lynch et al. (2017))
neurotoxicity (inhibition, acute dosing; central nervous system, cardiovascular; source: Lynch et al. (2017))
pain (activation, acute dosing; central nervous system, cardiovascular; source: Lynch et al. (2017))
psychosis (inhibition, chronic or acute dosing; central nervous system, cardiovascular; source: Lynch et al. (2017))
stereotypy (inhibition, chronic dosing; central nervous system, cardiovascular; source: Lynch et al. (2017))
Gene: Protein-coding gene on chromosome 19 (48,393,668 to 48,444,931, forward strand). Ensembl gene ENSG00000105464.
Subcellular location: Cell membrane; Postsynaptic cell membrane
Pathways (Reactome):
Neuronal System: Assembly and cell surface presentation of NMDA receptors; Long-term potentiation; Negative regulation of NMDA receptor-mediated neuronal transmission; Neurexins and neuroligins; Ras activation upon Ca2+ influx through NMDA receptor; Synaptic adhesion-like molecules; Unblocking of NMDA receptors, glutamate binding and activation
Signal Transduction: RAF/MAP kinase cascade
Gene Ontology:
Molecular function: glutamate-gated calcium ion channel activity; glutamate-gated receptor activity; NMDA glutamate receptor activity; protein binding; transmitter-gated monoatomic ion channel activity involved in regulation of postsynaptic membrane potential; glutamate binding; ligand-gated monoatomic ion channel activity; ligand-gated monoatomic ion channel activity involved in regulation of presynaptic membrane potential; monoatomic cation channel activity; monoatomic ion channel activity; signaling receptor activity; voltage-gated monoatomic cation channel activity
Biological process: calcium ion transmembrane import into cytosol; monoatomic cation transmembrane transport; brain development; excitatory chemical synaptic transmission; excitatory postsynaptic potential; ionotropic glutamate receptor signaling pathway; long-term synaptic potentiation; positive regulation of excitatory postsynaptic potential; positive regulation of synaptic transmission, glutamatergic; regulation of monoatomic cation transmembrane transport; regulation of neuronal synaptic plasticity; regulation of synaptic plasticity; synaptic transmission, glutamatergic; calcium-mediated signaling; cellular response to L-glutamate; monoatomic ion transport; regulation of presynaptic membrane potential
Cellular component: NMDA selective glutamate receptor complex; plasma membrane; endoplasmic reticulum membrane; postsynaptic density membrane; postsynaptic membrane; glutamatergic synapse; hippocampal mossy fiber to CA3 synapse; membrane; presynaptic active zone membrane; presynaptic membrane; synapse
Genetic constraint (gnomAD): Loss-of-function variants: 34 observed, 70.5 expected, observed/expected ratio (o/e) 0.48, 90% interval 0.37 to 0.64. The synonymous counts are far from expectation, so gnomAD's model fits this gene poorly and the ratio says little. Missense variants: 1,311 observed, 1,349.4 expected, observed/expected ratio (o/e) 0.97, 90% interval 0.93 to 1.02. Synonymous variants: 716 observed, 592.97 expected, observed/expected ratio (o/e) 1.21, 90% interval 1.13 to 1.28.
Gene-disease validity (ClinGen):
ClinGen rates the evidence that GRIN2D causes each of these diseases.
complex neurodevelopmental disorder (autosomal dominant): Definitive. A disorder that involves more than one phenotype associated with the central nervous system, including but not limited to intellectual disability, autism, and seizures (epilepsy).
Homologues: Orthologues: macaque GRIN2D (99% identical), dog GRIN2D (98% identical), pig GRIN2D (98% identical), mouse Grin2d (97% identical), rat Grin2d (96% identical), chimpanzee GRIN2D (79% identical), tropical clawed frog grin2d (59% identical), rabbit GRIN2D (58% identical), guinea pig GRIN2D (58% identical), zebrafish grin2da (53% identical), zebrafish grin2db (46% identical), Drosophila melanogaster Nmdar2 (21% identical), and 31 more. Paralogues in human: GRIN2C (43% identical), GRIN2A (40% identical), GRIN2B (38% identical), GRIN3B (19% identical), GRIN3A (18% identical), GRIK3 (15% identical), GRIN1 (15% identical), GRIK5 (15% identical), GRIA4 (15% identical), GRIK1 (15% identical), GRIK2 (14% identical), GRIA1 (14% identical), and 5 more.
Diseases named in the same sentence as GRIN2D in open-access papers:
GRIN2D is named in the same sentence as 69 diseases in open-access papers, as found by Europe PMC text mining. Sharing a sentence is not in itself a finding about the gene and the disease. The quoted sentences say what the papers report.
epilepsy (14 papers, 2014 to 2025). A brain disorder characterized by episodes of abnormally increased neuronal discharge resulting in transient episodes of sensory or motor neurological dysfunction, or psychic dysfunction. "Individuals with Coffin-Siris syndrome and GRIN2D-related developmental and epileptic encephalopathy are also at an elevated risk for a seizure disorder." (PMID 39144847, 2024). "Epilepsy associated with this GRIN2D mutation is refractory to conventional anti-epileptic medications." (PMID 33397303, 2021). "In epilepsy, we need to further understand the unique characteristics of GRIN2D mutations in neurological function and pathology, which is conducive to the treatment of refractory epilepsy." (PMID 35069111, 2021). "In a novel GRIN2D variant with epileptic encephalopathy, GRIN2D mutation-related epilepsy is found to be refractory to conventional AEDs." (PMID 35069111, 2021). "Besides AD, GRIN2A and GRIN2D are NMDARs, whose associated encephalopathies range from intellectual disability to epilepsy-aphasia spectrum phenotypes." (PMID 40727427, 2025). "Given that ketamine, another FDA-approved NMDAR antagonist, is currently widely used to treat status epilepticus, and has been used to treat refractory epilepsy in patient with a GRIN2D mutation, we evaluated its neuroprotective profile in GluN2A-P552R mediated neurotoxicity." (PMID 34776984, 2021). "Among these, GRIN2A, GABRB3, and GRIN2D have been reported previously, supporting their roles in epilepsy pathophysiology." (PMID 40313715, 2025). "Of note, variants among the GRIN3A are considered to be more relevant to autism spectrum disorders or schizophrenia, while GRIN1, GRIN2A, GRIN2B, and GRIN2D are more epilepsy-related." (PMID 38075685, 2023). "GRIN1 and GRIN2D code for subunits in the NMDA (N-methyl-D-aspartate) receptors and pathological variants are associated with a severe neurological phenotype including epilepsy." (PMID 40290421, 2025). "The effectiveness of memantine on drug‐resistant early‐onset epilepsy in individuals with gain‐of‐function GRIN2 variants (GRIN2A, GRIN2B and GRIN2D) is mixed, and previously, memantine treatment did not improve seizure frequency in four patients with GRIN2B gain‐of‐function mutations." (PMID 40827489, 2025).
schizophrenia (14 papers, 2013 to 2025). A major psychotic disorder characterized by abnormalities in the perception or expression of reality. "They report that specific combinations of four SNPs within the GRIN2D gene were significantly associated with schizophrenia." (PMID 37511595, 2023). "GRIN1, GRIN2A, GRIN2B, GRIN2C, and GRIN2D all encode subunits of the N-methyl-D-aspartate receptor (NMDAR), which has been shown to be involved in the development of schizophrenia." (PMID 34946799, 2021). "Among the detected autoantigens, higher IgG reactivity in subjects with schizophrenia, as compared to psychiatrically healthy subjects, was found against the glutamate ionotropic receptor NMDA type subunit 2D (anti-GluN2D)." (PMID 33208725, 2020). "A recent mutation-screening study also identified an ultra-rare, loss-of-function splice-site mutation (c.1412G>A) in the exonic region of the GRIN2D gene, which may lead to the creation of a truncated, nonfunctional GluN2D receptor, thereby contributing to schizophrenia risk." (PMID 37511595, 2023).
Epileptic encephalopathy (10 papers, 2020 to 2024). A condition in which epileptiform abnormalities are believed to contribute to the progressive disturbance in cerebral function. "Mutations in genes encoding NMDAR subunits, such as GRIN1, GRIN2A, GRIN2B, GRIN2C, and GRIN2D, have been linked to various epileptic phenotypes, ranging from focal and generalized seizures to severe epileptic encephalopathies." (PMID 39596430, 2024). "Another group generated iPSCs from fibroblasts of a developmental and epileptic encephalopathy (DEE) patient carrying a de novo heterozygous pathogenic variant of GRIN2D." (PMID 39596430, 2024). "As a subunit of NMDAR, GRIN2D is known to be involved in developmental and epileptic encephalopathies (DEEs) by forming the variants and changing channel open probability." (PMID 37553583, 2023). "Recent studies have shown that Grin2d genetic variants are linked to developmental and early infantile epileptic encephalopathy." (PMID 37156612, 2023). "A few case series have shown that GRIN2D variants are linked to developmental and epileptic encephalopathy." (PMID 33397303, 2021). "In this article, we report a novel GRIN2D variant, namely c.2021C > A (p.T674K) in a neonate with intractable epileptic encephalopathy." (PMID 33397303, 2021). "In this study, we describe a novel de novo mutation in GRIN2D in a neonate with intractable epileptic encephalopathy." (PMID 33397303, 2021). "GRIN2D is a ligand-gated ion channel with high calcium permeability that causes intracellular calcium overload in pathological states contributing to induce developmental and epileptic encephalopathies." (PMID 36204112, 2022). "However, GRIN2D dominant mutations can cause severe epileptic encephalopathy, which can be treated with NMDAR channel blockers." (PMID 35069111, 2021). "A novel variant of GRIN2D was identified in a neonate with epileptic encephalopathy." (PMID 33397303, 2021). "GRIN2D encoded N-methyl-D-aspartate receptor (NMDAR) subunit ε-4, which interacted with NMDA and was involved in developmental and epileptic encephalopathy." (PMID 35646712, 2022).
Alzheimer disease (7 papers, 2011 to 2025). A progressive, neurodegenerative disease characterized by loss of function and death of nerve cells in several areas of the brain leading to loss of cognitive function such as memory and language. "In a genome-wide association study of Alzheimer's disease, it was found that the expression of the brain messenger glutamate receptor Grin2d was reduced, potentially leading to impaired synaptic function, which is crucial for communication between nerve cells in the brain." (PMID 40413074, 2025). "We identified several proteins involved in the Alzheimer's disease pathway, including NMDA receptor (NMDARs) subunits (GRIN1, GRIN2B, and GRIN2D)." (PMID 40047119, 2025).
colorectal cancer (6 papers, 2016 to 2025). A primary or metastatic malignant neoplasm that affects the colon or rectum. "For example, in pancreatic and colorectal cancer, GRIN2D was overexpressed in patients’ tissues at both the mRNA and protein levels." (PMID 40535770, 2025). "ACCN2 has been shown to promote tumor growth and metastasis in breast cancer, and GRIN2D is an angiogenic tumor marker in colorectal cancer." (PMID 38177502, 2024). "In a study on colorectal cancer, GRIN2D was detected to be overexpressed in patients’ tissues at both mRNA and protein levels, and the function on promoting angiogenesis was identified in cellular assay." (PMID 37553583, 2023). "In colorectal cancer, GRIN2D overexpression was observed in blood vessels of tumor tissues, promoting angiogenesis." (PMID 37553583, 2023). "GRIN2D was shown to have vessel-restricted expression in colorectal cancer by RTqPCR and IHC analysis." (PMID 26943033, 2016). "The analysis identified GRIN2D to be positively expressed on the vessels of 40% of colorectal cancers, but only 10% of healthy colon samples." (PMID 26943033, 2016). "GRIN2D shows a promising tumour specific endothelial expression profile in a number of tumours, in particular colorectal cancer." (PMID 26943033, 2016). "In conclusion, GRIN2D is a promising vascular target in colorectal cancer for both treatment and prognostication." (PMID 26943033, 2016). "This analysis determined that the vessels in colorectal cancer stain strongly for GRIN2D, however, vessels in the healthy colon, marked by PECAM-1 staining do not stain for GRIN2D." (PMID 26943033, 2016). "For example, GRIN2D is overexpressed in colorectal cancer and can promote angiogenesis." (PMID 37553583, 2023). "Endothelial GRIN2D has been shown to promote angiogenesis in colorectal cancer." (PMID 36046118, 2021). "In order to investigate whether the expression of GRIN2D has any prognostic value in colorectal cancer, 90 colorectal tumours were stained for GRIN2D." (PMID 26943033, 2016). "Intriguingly GRIN2D expression in the vessels of colorectal cancer appears to be strongly associated, albeit not significantly so, with improved patient survival." (PMID 26943033, 2016). "GRIN2D expression was shown to be specific to colorectal cancer vessels by RTqPCR and IHC analysis." (PMID 26943033, 2016). "Sections of colorectal cancer and healthy colon were stained for PECAM-1 (a marker of endothelium) and GRIN2D by IHC." (PMID 26943033, 2016).
breast carcinoma (5 papers, 2023 to 2024). "Additionally, GRIN2D can be used as an executor controlled by miR-129-1-3p to regulate breast cancer cell infiltration and migration." (PMID 38022687, 2023). "In breast cancer, the research on miR-129-1-3p illustrated that it acted as a tumor repressor and bound with GRIN2D, but no further detailed work on GRIN2D in breast cancer functionally and mechanically." (PMID 37553583, 2023).
depression (5 papers, 2022 to 2025). "Risk for AD, low educational attainment, low cognitive ability and risk for major depressive disorder were all related to lower GRIN2D expression (and the expression of two other nearby genes)." (PMID 37794492, 2023). "The same expression profile, i.e., a predicted decrease of GRIN2D and ZSWIM9 levels but increased SLC17A7 levels, was also associated with increased risk for AD, lower educational attainment, lower cognitive ability, and higher risk of major depressive disorder across several independent studies." (PMID 37794492, 2023).
developmental and epileptic encephalopathy (5 papers, 2023 to 2025). An epilepsy associated with developmental impairment that may be due to either the underlying etiology or the superimposed epileptic activity, or both. "The results revealed patient was heterozygous for three different sequence variants (KMT2E, ARID1A, and GRIN2D) that were consistent with autosomal dominant genetic disorders (O’Donnell-Luria-Rodan syndrome, Coffin-Siris syndrome, and GRIN2D-related developmental and epileptic encephalopathy)." (PMID 39144847, 2024). "Recently, genetic variation within the GRIN2D gene, which encodes the GluN2D subunit of the NMDAR, has been associated with a set of early-onset neurological diseases, notably developmental and epileptic encephalopathy (DEE)." (PMID 35794776, 2023).
Intellectual disability (3 papers, 2020 to 2025). "Mutations in GRIN1 (which encodes the GluN1 subunit), GRIN2B (GluN2B), and GRIN2D (GluN2D), expressed during embryonic development, display more severe clinical phenotypes, including severe intellectual disability and developmental delay, than GRIN2A (GluN2A) mutations." (PMID 32197322, 2020).
triple-negative breast carcinoma (3 papers, 2022 to 2025). An invasive breast carcinoma which is negative for expression of estrogen receptor (ER), progesterone receptor (PR), and human epidermal growth factor receptor 2 (HER2). "MiR-129-1-3p has also been reported to play a role in triple-negative breast cancer by targeting GRIN2D and inhibiting tumor cell growth." (PMID 38818039, 2024). "In a study conducted in triple-negative breast cancer (MDA-MB-231) cells, the effect of miR-129-1-3p targeting the highly expressed Grin2d gene was evaluated and it was found that this miRNA caused suppression of important mechanisms such as cell growth and migration by suppressing Grin2d." (PMID 40579643, 2025).
alcoholics (2 papers, 2014 to 2022). "Interestingly, the GO term “alcoholism” was enriched in genes associated with the “CGI-free intergenic UMR” category, including Shc3, Shc4, Araf, Fosb, Hdac11, Adcy5, Creb3l2, Gnai2, Grin2d, and Ppp1r1b." (PMID 35205351, 2022).